CTDSP2 (CTD small phosphatase 2)
Description:
Preferentially catalyzes the dephosphorylation of 'Ser-5' within the tandem 7 residue repeats in the C-terminal domain (CTD) of the largest RNA polymerase II subunit POLR2A. Negatively regulates RNA polymerase II transcription, possibly by controlling the transition from initiation/capping to processive transcript elongation. Recruited by REST to neuronal genes that contain RE-1 elements, leading to neuronal gene silencing in non-neuronal cells. May contribute to the development of sarcomas.
Synonyms: SCP2; OS4; PSR2
Tractability: PROTAC: ubiquitination databases record sites on it.
Gene: Protein-coding gene on chromosome 12 (57,819,927 to 57,846,729, reverse strand). Ensembl gene ENSG00000175215.
Subcellular location: Nucleus
Subcellular location (Human Protein Atlas): Nucleoplasm; Mitochondria
Pathways (Reactome):
Cellular responses to stimuli: XBP1(S) activates chaperone genes
Gene Ontology:
Molecular function: protein binding; RNA polymerase II CTD heptapeptide repeat phosphatase activity; phosphatase activity; protein serine/threonine phosphatase activity
Biological process: protein dephosphorylation; regulation of transcription by RNA polymerase II
Cellular component: nucleoplasm; nucleus
Genetic constraint (gnomAD): Loss-of-function variants: 9 observed, 30.75 expected, observed/expected ratio (o/e) 0.29, 90% interval 0.17 to 0.51. The upper end of that interval is the gene's LOEUF score, 0.51, which puts it in group 2 of 6, group 1 being the genes least tolerant of losing a copy. Missense variants: 266 observed, 361.99 expected, observed/expected ratio (o/e) 0.73, 90% interval 0.66 to 0.81. Synonymous variants: 134 observed, 140.03 expected, observed/expected ratio (o/e) 0.96, 90% interval 0.83 to 1.1.
Homologues: Orthologues: chimpanzee CTDSP2 (100% identical), macaque CTDSP2 (100% identical), guinea pig CTDSP2 (99% identical), dog CTDSP2 (98% identical), pig CTDSP2 (96% identical), mouse Ctdsp2 (94% identical), rat Ctdsp2 (90% identical), tropical clawed frog ctdsp2 (80% identical), zebrafish ctdsp2 (73% identical), Drosophila melanogaster hzg (56% identical), Caenorhabditis elegans scpl-1 (53% identical). Paralogues in human: CTDSPL (62% identical), CTDSP1 (60% identical), CTDSPL2 (35% identical), CTDNEP1 (30% identical), TIMM50 (23% identical).
Diseases named in the same sentence as CTDSP2 in open-access papers:
CTDSP2 is named in the same sentence as 21 diseases in open-access papers, as found by Europe PMC text mining. Sharing a sentence is not in itself a finding about the gene and the disease. The quoted sentences say what the papers report.
breast carcinoma (2 papers, 2023 to 2024). "Liu confirmed that the overexpression of miR-26a in human breast cancer cells significantly increased the expression of the host genes CTDSPL and CTDSP2, suggesting a self-perpetuating loop of miR-26a." (PMID 37373175, 2023).
rectal cancer (2 papers, 2019 to 2022). A primary or metastatic malignant neoplasm that affects the rectum.
bone osteosarcoma (1 paper, 2019). A usually aggressive malignant bone-forming mesenchymal neoplasm arising from the bone. "Overexpression of CTDSP2 reduced the number of cells in S-phase and inhibited cell cycle progression in a bone osteosarcoma cell line." (PMID 31774910, 2019).
brain cancer (1 paper, 2022). A primary or metastatic malignant neoplasm affecting the brain. "Among the cohorts with sufficient sample sizes for RNA-seq analysis, we find that an enhancer of CTDSP2 is a putative driver in brain cancer (glioblastoma multiforme), and the SVs are associated with its differential expression." (PMID 36163358, 2022).
brain tumors (1 paper, 2019). "CTDSP2 (also known as OS4, PSR2, and SCP2) is located in the genomic region that is frequently amplified in sarcomas and brain tumors." (PMID 31774910, 2019).
colorectal cancer (1 paper, 2019). A primary or metastatic malignant neoplasm that affects the colon or rectum.
female infertility (1 paper, 2021). Diminished or absent ability of a female to achieve conception. "APCDD1 is involved in adipogenic differentiation, CTDSP2 is a target gene of FOXO and regulates cell cycle progression, EZH2 is an important regulator in the female reproductive tract, MGA4A is involved in embryo lethality and female infertility, and RHOQ regulates mitochondrial function." (PMID 34639162, 2021).
glioblastoma (1 paper, 2022). The most malignant astrocytic tumor (WHO grade IV). "However, one prominent example supported by RNA-seq data is CTDSP2 enhancer, which is a candidate driver in glioblastoma." (PMID 36163358, 2022).
kidney tumors (1 paper, 2023). "CTDSPL inactivation in kidney tumors may be mediated by mechanisms different from CTDSP1 and CTDSP2." (PMID 37629167, 2023).
lymphoma (1 paper, 2011). A malignant (clonal) proliferation of B- lymphocytes or T- lymphocytes which involves the lymph nodes, bone marrow and/or extranodal sites. "Myc was previously reported to regulate the expression of miRNAs, including miR-26a and miR-26b in P493 lymphoma cells, by direct binding to their host Pol II gene promoters (CTDSPL, CTDSP2, CTDSP1)." (PMID 21941025, 2011).
neuroblastoma (1 paper, 2019). Neuroblastoma (NB) is the most common solid, extracranial childhood tumor. "However, miR-26a inhibits the expression of CTDSP2 in neuroblastoma cell line in vitro." (PMID 31774910, 2019).
prostate carcinoma (1 paper, 2011). A carcinoma that arises from epithelial cells of the prostate gland. "We found a significant enrichment of MYC at the promoters of CTDSPL, CTDSP2 and CTDSP1 in both prostate cancer cell lines." (PMID 21941025, 2011).
cancer (8 papers, 2013 to 2025). A tumor composed of atypical neoplastic, often pleomorphic cells that invade other tissues. "This included genes in which upregulation is implicated in cancer (CTDSP2, CASC3, PGF) and those that are thought to be involved in tumor suppression (SASH1, HIPK2)." (PMID 23406646, 2013). "Altogether, these data suggest tumor suppressor activity of CTDSPL, CTDSP1, and CTDSP2 genes in different types of cancer." (PMID 31774910, 2019).
tumor (7 papers, 2013 to 2025). "The tumor suppressor properties of CTDSP2 and CTDSPL has also been reported in recent studies." (PMID 32397221, 2020). "CTDSP2 and CTDSPL also inhibit tumor growth and angiogenesis through dephosphorylation of RB and tumor-suppressor protein promyelocytic leukemia (PML)." (PMID 32397221, 2020). "In ccRCC cell lines 786-O and A-498, the ectopic expression of CTDSP1 suppressed proliferation, migration, and invasion of tumor cells in vitro and in vivo (no data regarding CTDSP2 and L)." (PMID 37629167, 2023). "Our data confirmed that CTDSP1 and CTDSPL (but not CTDSP2) exerts tumor suppressive activity in ccRCC." (PMID 37629167, 2023). "Additionally, the functionality of CTDSP2 and CTDSPL, such as their catalytic activity against RNAP II CTD peptide and their tumor-suppressing role, also overlaps with that of CTDSP1." (PMID 32397221, 2020).
CTDSP2 also shares sentences with these, for which no sentence is quoted: infection (4 papers); ovarian carcinoma (3); co-infection (1); mesothelioma (1); microphthalmia (1); otosclerosis (1); sarcoma (1).